KRAS (KRas proto-oncogene, GTPase)
Diseases named in the same sentence as KRAS in open-access papers (continued):
Sharing a sentence is not in itself a finding about the gene and the disease.
tumor (continued). "QTX3034 (Quanta Therapeutics), RSC-1255 (RasCal Therapeutics), and YL-17231 (TEB-17231, Shanghai YingLi Pharmaceutical Co., Shanghai, China) are other pan-RAS inhibitors that have also demonstrated durable inhibition of KRAS signaling in vivo and tumor growth in vitro." (PMID 39337530, 2024). "Neither KRAS c.34G>T mutants nor other KRAS mutants were associated with other features including the tumor tissue abundance of F. nucleatum (F. animalis), pks+E. coli, Bifidobacterium, or (enterotoxigenic) B. fragilis." (PMID 39039804, 2024). "It is interesting to note that this study concluded that surface markers' ability to enrich for TPCs was influenced by the genotype of the tumor; in KRAS mutant mice, tumors containing only KRAS mutations did not exhibit tumors that Sca-1 enriched for TPCs." (PMID 39547513, 2024). "Also, we found some interesting cases, two cases that carried EGFR L858R and T790M co‐mutation in one tumor and another tumor with only EGFR 19del, and 1 case with two KRAS hotspots in the same tumor." (PMID 38348924, 2024). "Similarly, tumor cells defective in the RAS/KRAS pathway interact with immune cells in the TME by secreting a series of cytokines, such as TGF-β, IL-8, and IL-6, which are involved in macrophage reprogramming and the regulation of Treg differentiation." (PMID 38879686, 2024). "Furthermore, we demonstrated that the limited in vivo efficacy of CDK9i in KRAS‐mutant cancers can be attributed not only to the activated pro‐survival signaling in tumor cells but also to the immunosuppressive TME orchestrated by the complement system." (PMID 39254172, 2024). "Although research is still in its early stages, the success of these studies suggests that KRAS-targeted TCR-T cell therapies could lead to long-term tumor remission in patients with limited treatment options." (PMID 39439803, 2024). "KRAS mutations detected in cfDNA were eventually classified as clonal hematopoiesis mutations, and not tumor-derived mutations." (PMID 39064004, 2024). "The benefit provided by EGFR mAbs in KRAS WT mCRC is associated with left-sided primary tumour location, younger patient age and absence of NRAS or BRAF mutations." (PMID 38402342, 2024). "Interestingly, in CRC cell lines, the tumor-suppressing function of ODC depends on KRAS mutations, as neither loss- nor gain-of-function of ODC affects proliferation or migration in the KRAS wild-type Caco-2 cell line, both in vitro and in vivo." (PMID 39795950, 2024). "The differences in apoptosis induction and proliferative indices reflect key differences in how normal tissues respond and adapt to RAS inhibition with RMC-6236 compared with tumors driven by mutant KRAS, providing a rational basis for the tumor selectivity of RAS inhibition." (PMID 38593348, 2024).
tumor (continued). "In this manuscript, we performed a relatively large-scale study to determine the correlation between the percentage of tumor cellularity estimated by certified anatomic pathologists and VAFs of well-studied driver mutations detected in key oncogenes (i.e., BRAF, EGFR, KRAS, and NRAS)." (PMID 38397405, 2024). "CDKN2A and KRAS occur in the early stages of tumor development." (PMID 39040449, 2024). "Additionally, GC1 KO in intestinal epithelial cells lowers tumor burden in KRAS mutant mice compared to wild-type GC1 mice." (PMID 39795950, 2024). "Furthermore, a close correlation has been shown between oncogenic KRAS expression and pleiotropic metabolic changes that occur as primary events supporting tumorigenesis and subsequently sustaining tumor progression." (PMID 39329730, 2024). "Tumor start, maintenance, and progression are all influenced by the presence of oncogenic KRAS." (PMID 38827026, 2024). "Another study revealed that depleting B cells with a KRAS small-molecule inhibitor did not significantly improve tumor progression, suggesting that B cell-associated PDAC progression occurs in a KRAS mutation-independent manner." (PMID 38982491, 2024). "Oncogenes, such as KRAS, CTNNB1 (β-catenin), and HER2/neu (human epidermal growth factor receptor 2), when mutated or activated, induce the stimulation of proliferation and extended survival of tumor cells, promoting the invasion and metastases of EC." (PMID 38893147, 2024). "Furthermore, we observed an upregulation of FAK in specific tumor types with gene mutations or aberrant protein expression, such as BRAF/KRAS mutations, CDH1 deletions, EGFR or HER2 overexpression, and mediated drug resistance processes." (PMID 38410129, 2024). "Similarly to activating mutations in KRAS, their counterparts in NRAS also speed up tumor progression." (PMID 39456660, 2024). "KRAS overexpression has been correlated to tumor metastasis and poor prognosis." (PMID 38637684, 2024). "Some studies observed that KRAS mutations more frequently in tumours with CDX2 expression, while other studies did not." (PMID 38439814, 2024). "Meanwhile, the study combined RNA-seq and FISH analyses to compare the transcriptional levels and the expression levels in tumor cells; these cases showed significantly increased transcription levels of KRAS and CRKL, as well as consistent high abundance signals in the nucleus." (PMID 38790424, 2024). "ADC patients harboring STK11 mutation concurring with KRAS mutations show lower or a lack of PD-L1 expression on tumor cells and have a lower index of infiltrating CD3+ and CD8+ T lymphocytes." (PMID 38397927, 2024). "The findings indicated that CSI may augment the antitumor efficacy of erlotinib in tumor-bearing mice by inhibiting KRAS and p-ERK1/2, highlighting the potential of this combination therapy for PDAC management." (PMID 39770538, 2024). "KRAS mutations have been observed especially in the endometrioid subtype and are responsible for the activation of its MAPK/ERK signaling pathway, which contributes to the growth and progression of the tumor." (PMID 38893147, 2024).
tumor (continued). "As KRAS mutations were largely unique to patients with LUAD, we next explored the relationship between KRAS mutation status and PDL1 expression while controlling for tumor histology." (PMID 39113608, 2024). "The distinct anti-proliferative, pro-apoptotic effects of RMC-7977 in KRAS-mutant tumour cells relative to normal tissues are consistent with the concept of oncogene dependence and explain the remarkable extension of overall survival that we observed in the highly chemoresistant KPC mouse model." (PMID 38588697, 2024). "Mechanistically, KRAS has major implications on tumor metabolism." (PMID 38886847, 2024). "Both KRAS mutations and amplifications, as well as NRAS mutations have been identified as mechanisms of resistance to cetuximab and panitumumab both in liquid biopsy and tumor biopsy specimens." (PMID 38711991, 2024). "Recent “buzzwords” like “tumor-infiltrating lymphocytes,” “checkpoint blockade,” and “PD-1 blockade” suggest that there is a focused shift towards understanding and enhancing the immunotherapeutic approaches for treating KRAS-induced malignancies." (PMID 39252322, 2024). "Additionally, SHP2 inhibitors in combination with KRAS G12C inhibitors influenced the tumor microenvironment in murine models of PDAC." (PMID 38668053, 2024). "Targeting KRAS alone appears insufficient to tackle tumor growth effectively." (PMID 39061234, 2024). "Another tumor suppressor pathway inactivated by oncogenic KRAS that could be responsible for pancreatic ADM is the SAG-SHOC2 axis." (PMID 38391963, 2024). "Indeed, even when KRAS‐mutant cells are present, they often represent a small proportion of the tumour." (PMID 38887984, 2024). "There is generally a negative correlation between tumor PD-L1 expression and response to immunotherapy and the presence of oncogene driver mutations, except for KRAS and partially BRAF and met exon 14 skipping mutations." (PMID 38953007, 2024). "Studies have shown that MET gene amplification can often coexist with other tumor driver genes in NSCLC, such as EGFR and KRAS mutations and ALK and ROS1 fusions, indicating that MET gene amplification may not act as an intrinsic driver factor within tumors." (PMID 39582541, 2024). "As proven in the present study, the list of genes from the 44-gene panel more frequently mutated in BOT compared to the other tumor groups (FANCB, SEM1, FANCA, BRCA2, CHEK2, MUTYH, RAD50) was much longer than analogically altered genes in the hot-spot panel (KRAS only)." (PMID 39456660, 2024). "KRAS-mutant CRC cancer is linked to decreased survival and increased tumor aggressiveness." (PMID 39519596, 2024). "The importance of the Hippo pathway in pancreatic cancer development was demonstrated when YAP-TAZ cues promoted tumor progression despite the absence of KRAS mutation." (PMID 38672552, 2024). "Only 9.7% of KRAS VAFs (R2 = 0.097) may be statistically significantly correlated with tumor cellularity." (PMID 38397405, 2024).
tumor (continued). "In tumor cells activated by tyrosine kinase receptor or the KRAS oncogene, AKT(Protein Kinase B, PKB) phosphorylates serine at 90 of PCK1, and phosphorylated PCK1 translocates to the endoplasmic reticulum and loses its original gluconeogenic metabolic enzyme function." (PMID 39578429, 2024). "While KRAS-mutated tumours showed less infiltration of immune cells compared to wild-type KRAS tumours, in particular cytotoxic T cells and Th1 cells, BRAF-mutated tumours showed a higher infiltration of these immune cells compared to wild-type BRAF tumours." (PMID 38040818, 2024). "Furthermore, qRT-PCR analysis of tissue samples demonstrated a significant upregulation of KRAS in tumor tissues compared to normal tissues." (PMID 38309290, 2024). "The development of polyclonal tumours from clones with distinct Apc mutational profiles suggests that just right conditions for tumour initiation can be achieved by cooperation between founder clones reciprocating in their perturbation of APC–MYC and KRAS pathways." (PMID 39478206, 2024). "Mechanistically, KRAS drives tumor development and progression through various signaling pathways." (PMID 38763973, 2024). "However tumor cells after KRAS-driven metabolic reprogramming can be blocked in the S or G2/M phase due to glutamine deprivation and therefore can be effectively targeted by transaminase inhibitors or S-phase-specific toxic compounds during the therapy." (PMID 38172980, 2024). "Here, survival analyses of infiltrating cytotoxic T cells at the tumour front showed a strong prognostic role for cytotoxic T cells in CRC independent of KRAS- and BRAF-mutational status." (PMID 38040818, 2024). "Moreover, it has been found that various drug delivery systems can be internalized by KRAS-mutant tumor cells through macropinocytosis, opening up the possibility of using macropinocytosis as an emerging drug delivery method for therapeutic agents." (PMID 38424455, 2024). "Numerous studies have demonstrated that KRAS inhibition reverses immune suppression, causes a profound remodelling of the tumour immune microenvironment (TME) and activates anti-tumour immunity, which provides a window of opportunity for combination with immunotherapies." (PMID 39322643, 2024). "Our data suggest an alternative mechanism that may explain how KRAS‐mutant cells could promote survival of KRAS‐wild type cells in a heterogeneous tumour." (PMID 38887984, 2024). "Additionally, when comparing tumor samples from the sh-circ_0039787 group to control mice, a notable decrease in the expression of KRAS and Ki-67 was observed." (PMID 38309290, 2024). "Moreover, IK-595 has enhanced the efficacy of conventional chemotherapy drugs in KRAS-driven tumor models, broadening the potential clinical applications of IK-595." (PMID 38791529, 2024). "Also, tumor growth in xenograft mouse models was suppressed by KRAS siRNA encapsulated in iRGD-exosomes." (PMID 39355533, 2024). "Notably, when mice treated with both sotorasib and anti-PD-1 to clear KRAS G12C tumors were rechallenged with KRAS G12D tumor cells, an immune memory response halted the growth of the tumor, highlighting the adaptive immune reactions to shared antigens." (PMID 38668053, 2024). "Evaluate the relationship between VC intake and the survival of individuals with CRC, considering the presence or absence of KRAS or BRAF mutations in the tumor." (PMID 39130946, 2024). "Moreover, tumor-related gene mutations such as TTN, MUC16, and KRAS with a higher number in groups were also enriched in distinct groups." (PMID 38488909, 2024).
tumor (continued). "The efficacy of HuSC1-39 or MTI-31 to overcome KRAS inhibitor resistance in vivo is striking and the potential remodeling of tumor microenvironment (TME) may be involved in this setting." (PMID 38191673, 2024). "We used two approaches to identify the KRAS–RanGAP1 complex in tumor cells." (PMID 39528835, 2024). "We propose that this Rab11a‐exosome‐mediated mechanism contributes to the establishment of resistance in cetuximab‐sensitive cells and may explain why in cetuximab‐resistant tumours only some cells carry mutant KRAS." (PMID 38887984, 2024). "Moreover, Mutant KRAS tumor cell lines are more likely to amplify chromosome 12p, suggesting that enhancing the dose of oncogenic KRAS mutations is a beneficial trait (OR = 2.043, P = 0.0009)." (PMID 39294502, 2024). "Therefore, targeting the KRAS pathway along with mitochondrial respiration appears to be a potential target for the elimination of bulk tumor cells along with the dormant CSC population." (PMID 38474411, 2024). "In distal metastasis, the rapid regression of the tumor might occur when advanced or precursor lesions of KRAS vanish." (PMID 38827026, 2024). "KRAS G12V mutation was identified using liquid biopsy-based next-generation sequencing (no tumor tissue sample available due to technical constraints)." (PMID 38392077, 2024). "Notably, the mutant selection windows for BRAF and KRAS mutants took up most of the tumor area in this regime." (PMID 38386690, 2024). "However, strong correlations between the KRAS/BRAF mutational status and tumor budding have been reported." (PMID 38248029, 2024). "For example, SNVs were identified in PIK3CA and KRAS across different cancer types and similarly pangenomic markers, such as homologous recombination deficiency (HRD) and tumor mutational burden (TMB), for which clinical trials may be available." (PMID 38200255, 2024). "We did not detect KRAS mutations in four of the samples, either because they were KRAS wild-type or because there was no detectable tumor material in the sample." (PMID 39123450, 2024). "It has also been theorized that MEK1/2 inhibition may modulate the KRAS-mutant NSCLC tumor immune microenvironment via altered chemokine secretion and increased T-cell recruitment." (PMID 39337530, 2024). "Also, an in vivo study showed that delivery of miR-873 NPs reduced tumor growth by inhibiting KRAS expression in PDAC and TNBC xenograft–tumor models." (PMID 38893132, 2024). "This supports KRAS-independent tumor growth and confers resistance against KRAS inhibitors." (PMID 38957319, 2024). "Cases 1 and 3, in which no KRAS mutations were detected, had a mean target coverage in tumours of 746 and 461, respectively which indicates that these tumours are truly wild-type and that there are no sampling or technical issues resulting in false negatives." (PMID 38762572, 2024). "KRAS transmits signals from the cell surface to the nucleus, influencing tumor cell proliferation." (PMID 38983866, 2024). "Restoration of COX2 expression contributed to tumor relapse after prolonged KRAS inhibition." (PMID 38635884, 2024).